TNF (tumor necrosis factor)
Diseases named in the same sentence as TNF in open-access papers (continued):
Sharing a sentence is not in itself a finding about the gene and the disease.
Hyperglycemia (continued). "Significantly increased TNF-α production was observed in the placenta and the subcutaneous adipose tissue in women with GDM and noncontrolled hyperglycemia when compared with those with well-controlled GDM (i.e., normoglycemic)." (PMID 22462002, 2012). "Even acute hyperglycemia in non-diabetics has been reported to elevate plasma IL6 and TNFα concentrations." (PMID 23028447, 2012). "Hyperinsulinaemia in either the presence or the absence of hyperglycaemia induced enhanced mRNA levels of all measured genes (Pinsu < 0.05), except for NFKB1 (Pinsu = 0.09) and TNF (Pinsu = 0.16)." (PMID 18290856, 2008). "Lastly, a significant decrease in the expression of IL-6, TNF-α, and CCL2 was noted in the cornea at 7 days after hyperglycemia, whereas no significant alterations in the expression of these genes could be noted at 14 or 28 days of hyperglycemia." (PMID 39749321, 2024). "In addition to the eventual presence of hyperglycemia, the most obvious difference between the non-diabetic and diabetic patients concerned the higher HOMA-IR index and lower TNF-α value recorded in the diabetic patients than in the non-diabetic one." (PMID 32164195, 2020). "Similarly, HRECs stimulated with TNF + HG treatment demonstrated activation of IRE1α pathway but not PERK and ATF6 suggesting that inflammation and hyperglycemia in endothelial cells results in diverse UPR pathways." (PMID 31346222, 2019). "However, hyperglycemia does not prevent their intrinsic ability to function, as demonstrated by the fact that PMA/I stimulation, which circumvents TCR stimulation, did not affect TNF-α expression." (PMID 38214784, 2024). "Stimulating lipolysis in adipocyte, without inhibiting TNF-α, might be useless, because TNF-α is known to promote lipolysis and inhibit adipocyte maturation, which contributes to higher hepatic glucose production and hyperglycemia." (PMID 35209178, 2022). "Fat accumulation in adipose tissue, liver, skeletal muscle, heart, and pancreas may increase systemic oxidative stress independent of hyperglycemia as well as adipocytokines or adipokines such as plasminogen activator inhibitor−1 (PAI-1), tumor necrosis factor (TNF)-α, resistin, and leptin." (PMID 30564116, 2018).
Hypertension (772 papers, 2006 to 2026). The presence of chronic increased pressure in the systemic arterial system. "A rise in mean arterial pressure expressed a two-fold increase in plasma TNF-α in pregnant rodents, causing TNF-α induced hypertension." (PMID 41394354, 2025). "Pro-inflammatory cytokines, such as tumor necrosis factor-alpha (TNF-α), are known to be associated with renal inflammation and hypertension." (PMID 40723823, 2025). "We observed IL-6 and TNF-α were also positively related to Clostridium-innocuum-group, which was classified as a risk factor for hypertension, with IL-1R2 (an inflammation-associated receptor) being identified as a significant mediator." (PMID 41154794, 2025). "Hypertension has been linked to higher levels of IL-6 and TNF-α, making the CNS more susceptible to neuroinflammatory injury." (PMID 39861166, 2025). "TNF-a is associated with the structural remodelling of the atrium, specifically the angiotensin-II-dependent histological changes seen in hypertension." (PMID 40005478, 2025). "Hypertension is strongly associated with increased circulating levels of proinflammatory cytokines such as IL‐1β, IL‐6, and TNF‐α." (PMID 40454610, 2025). "While elevated TNF-α levels can lead to blood pressure reduction, moderate increases have been linked to enhanced sodium chloride retention, contributing to hypertension." (PMID 40422564, 2025). "According to our findings demonstrated an association between the TNF-α-308G/A polymorphism and CAD patients with ≥50% obstruction, suggesting the necessity for additional investigations into the role of the TNF-α-308G/A polymorphism in hypertension." (PMID 39787106, 2025). "TCM also reduces the expression of inflammatory factors such as IL-6 and TNF-α, mitigating vascular injury caused by hypertension." (PMID 39717555, 2024). "CTLs, through the FASL-FAS system, induce apoptosis in target cells, and their production of cytokines like interferon-gamma (IFNγ) and tumor necrosis factor (TNF) has been linked to hypertension and renal damage in mice models." (PMID 38606081, 2024). "Heightened concentrations of TNF are associated with augmented vascular resistance and endothelial impairment, both of which are essential elements in the pathophysiology of hypertension." (PMID 39592923, 2024). "These cytokines, including interleukin-6 and tumor necrosis factor-alpha, can increase the inflammatory burden both locally and systemically, and these markers are closely associated with the development of hypertension." (PMID 39350272, 2024). "Elevated proinflammatory cytokines, such as IL‐6 and TNF‐α, have been closely associated with organ damage in both human subjects and animal models of hypertension." (PMID 38504425, 2024). "Inflammation markers, IL6 and TNFα, were found to be independent risk factors for hypertension in both normo- and prehypertensive subjects." (PMID 39558500, 2024). "TNF can trigger the activation of diverse signaling pathways, leading to structural and functional alterations in the vascular system that cause hypertension." (PMID 39592923, 2024). "In persons with fatty livers, elevated pro-inflammatory cytokines (e.g., TNF-α, IL-6) compromise arterial endothelial function, hence heightening the risk of hypertension." (PMID 39598120, 2024). "In the field of cardiovascular disease research, biomarkers such as C-reactive protein (CRP), interleukin (IL), and tumor necrosis factor-alpha (TNF-α) are considered to be associated with poor prognosis in patients with hypertension or coronary heart disease." (PMID 39234507, 2024). "TNF‐α, another proinflammatory cytokine primarily produced by T lymphocytes, shows heightened presence in various hypertension models and has been linked to increased production of reactive oxygen species (ROS) and vascular dysfunction." (PMID 38504425, 2024).
Hypertension (continued). "The activated T cells produce interferon-gamma (IFN-γ), interleukin 17A (IL-17A) and tumor necrosis factor-alpha (TNF-α) which causes vascular damage and lead to hypertension." (PMID 37342440, 2023). "On the other hand, TNF blockade, either using gene deficient mice or specific antagonists, can prevent the development of angiotensin II-induced hypertension." (PMID 36671012, 2023). "Second, reducing SCFAs leads to an increase in proinflammatory cytokines, including TGF-β1, TNF-α, IL-1β, and IL-6, which in turn causes a reduction in glomerular filtration rate and consequently results in hypertension." (PMID 37273529, 2023). "Another meta-analysis involving 1,092 patients with essential hypertension and 1,152 controls found a significant association between the TNFα G308A gene polymorphism with hypertension." (PMID 37201134, 2023). "T cells have also widely been linked to the development of hypertension and T cell production of TNF-α has been linked to the development of angiotensin II-dependent hypertension." (PMID 35413930, 2022). "The pro-inflammatory cytokine TNF-α has been implicated in BP control in both male and female experimental models of hypertension." (PMID 35413930, 2022). "The study has demonstrated that IL6 and TNF, as inflammatory factors, are independent risk factors for hypertension." (PMID 35360657, 2022). "Tumor necrosis factor-α (TNF-α) is another cytokine implicated in the vascular remodeling of hypertension, as it is essential for Ang-II-induced MMP-2 expression." (PMID 33923477, 2021). "We have previously shown ET-1 to be stimulated in response to TNF-α and to play an important role in hypertension associated with elevated TNF-α during pregnancy." (PMID 33407826, 2021). "Research studies have found that the plasma TNF-α concentration in the rat model of hypertension was obviously associated with a decrease in cardiac LVFS% and a lack of cardiac GSH." (PMID 34868392, 2021). "Both TNFα and Ang II are reported to be substantially elevated in SHRs; therefore, these peptides demonstrated potential in ameliorating hypertension-associated oxidative stress in vivo." (PMID 33671990, 2021). "Hypertension is associated with an increase in blood levels of pro-inflammatory cytokines such as TNF, IL-6, monocyte chemoattractant protein-1(MCP-1), and sICAM-1 which can contribute to BBB disruption." (PMID 34054705, 2021). "Commonly increased in arterial hypertension, interleukin-1β and TNF-α are cytokines associated with nuclear factor κB (NF-κB) translocation and transcription, which exacerbate inflammation, oxidative stress, and cell proliferation." (PMID 34777003, 2021). "Hypertension induced by chronic AngII administration was attenuated in mice either deficient in TNF‐α gene or subjected to pharmacological TNF‐α blockade." (PMID 34427402, 2021). "Increased serum levels of CRP, monocyte TNF-α secretion, and serum IL-6 concentrations were reported in patients with hypertension, suggesting a close association between inflammation and hypertension." (PMID 33937238, 2021). "For example, tumour necrosis factor‐α (TNF‐α), interleukin‐6 (IL‐6) and interleukin‐1β (IL‐1β) cause chronic low‐grade inflammation in hypertension." (PMID 34331512, 2021). "Prolonged mercury exposure increases the risk of developing hypertension through systemic inflammation, as demonstrated by elevated levels of serum inflammatory cytokines TNF-α, IL-2, IL-6 and anti-inflammatory cytokine IL-10." (PMID 33083327, 2020). "Elevated levels of IL-1β, IL-10, and TNF-α are also correlated with increased arterial stiffness associated with hypertension." (PMID 33265898, 2020). "Remarkably, the NO-deficient mouse model of hypertension is characterized by induced TNF-α generation and significant natriuretic response." (PMID 32149110, 2020).
Hypertension (continued). "The increase of inflammatory cytokines (TNF-α, IL-2, IL-6 and IL-10) in the serum indicates an increase of systemic inflammation and a risk of hypertension for the mercury-exposed population." (PMID 33083327, 2020). "High levels of several cytokines (such as TNF-α) and hypertension can cause the development of glomerulosclerosis, generating injuries similar to CKD." (PMID 33041804, 2020). "Another pro-inflammatory molecule, which has been proposed as a prognostic marker for CVD and risk for occurrence of hypertension during CKD is TNF-α." (PMID 30617956, 2019). "In turn, IL-17 induces IL-1β, IL-6, and TNF-α secretion, also associated with endothelial dysfunction and hypertension." (PMID 31186952, 2019). "JYYS granule has been a therapeutic drug for hypertension and early hypertension-caused renal damage by downregulating AngII and TNF-α level." (PMID 30598687, 2018). "TNF-α and IL-6 levels were associated with hypertension in all models (TNF-α: P<0.001; IL-6: model 1, P = 0.002; model 2, P = 0.029; model 3, P = 0.044)." (PMID 28837559, 2017). "Hypothalamic inflammation has been implicated in the pathogenesis of hypertension, with previous work reporting that an increase in hypothalamic TNFα raises AP." (PMID 28093508, 2017). "It has also been shown that infusion of tumor necrosis factor-α (TNF-α) directly induced hypertension in pregnant rats and is associated with significant increases in the expression of preproendothelin in the maternal vasculature, placenta, and kidney." (PMID 28264495, 2017). "TNF-α antagonist Etanercept reduces the hypertension caused by fructose feeding in rats and prevents the hypertension caused by angiotensin II infusion." (PMID 26989902, 2016). "The aim of this study was to investigate the overall incidence and risk of hypertension in RA patients who receive anti-TNF agents." (PMID 25860222, 2015). "Patients with cardiovascular disease and arterial hypertension are particularly concerned about safety, even if TNF antagonists favourably influence cardiovascular risk." (PMID 26633680, 2015). "The use of anti-TNF agent significantly increased the risk of developing hypertension (OR = 1.8896, 95% CI: 1.35–2.65)." (PMID 25860222, 2015). "The detected increase of hypertension risk has to be explained according to the notable effectiveness of anti-TNF treatment in RA patients and the short of replacement therapy in cases with serious disease activity adiaphorous to conventional DMARD therapy." (PMID 25860222, 2015). "In conclusion, our study suggests that the use of anti-TNF agent is associated with increased risk of developing hypertension." (PMID 25860222, 2015). "Our analysis, based on 6321 patients from 11 clinical trials, demonstrates that the pooled incidence of anti-TNF agents associated hypertension is 3.25% (95% CI: 1.51%–6.89%)." (PMID 25860222, 2015). "The overall incidence of hypertension associated with anti-TNF agent was 3.25% (95% CI: 1.51%–6.89%)." (PMID 25860222, 2015). "Despite some studies suggesting TNF-α as a potential marker of vascular inflammation, the causal role of this cytokine in the pathogenesis of hypertension is underexplored." (PMID 26504819, 2015). "Our result showed that the risk and incidence of hypertension among different anti-TNF agents are discrepant." (PMID 25860222, 2015). "Anti-TNF therapy is associated with a significantly increased risk of developing hypertension in patients with RA." (PMID 25860222, 2015). "This study also examined the associations of IL-6 and TNF-α with anthropometric measurement and the effect of co-morbidity with hypertension using rural and urban dwellers in the Ashanti region, Ghana." (PMID 26391589, 2015). "Hypertension is considered to cause elevation of inflammatory cytokines such as tumor necrosis factor-alpha (TNF-α), interleukin-6(IL-6)." (PMID 25474403, 2014).
Hypertension (continued). "We also found that prenatal LPS (0.79 mg/kg) exposure up-regulates IL-6 and TNF-a mRNA expression in fetus and causes hypertension in offspring rats." (PMID 24498431, 2014). "From these current studies ANG II and TNF-α were identified as key biomarkers of hypertension risk in the Saudi cohorts, which remained significant independent of DMT2, age or BMI." (PMID 23251471, 2012). "The tumor necrosis factor-alpha (TNFα) G308A gene polymorphism has been implicated in susceptibility to essential hypertension (EH), but study results are still controversial." (PMID 22536381, 2012). "Characteristics of the investigated studies of the association between the tumor necrosis factor-alpha G308A gene polymorphism and essential hypertension." (PMID 22536381, 2012). "IL-6 and TNF-a are inflammatory markers linked directly and indirectly to both hypertension and AF." (PMID 40005478, 2025). "In other experiments, TNF-α was downregulated through Cyp2c23 and upregulated through sEH, activation of NF-κB-mediated pathways, and increased renal cortical NF-kappa B activity that are involved in renal damage caused by multiple causes of hypertension." (PMID 38545112, 2024). "Meanwhile, in patients with chronic CSC, elevated plasma levels of IL-8, IL-6, and TNF-α were found to be associated with hypertension, shedding light on the potential role of these cytokines in the pathophysiology of chronic CSC and its associated comorbidities." (PMID 38835666, 2024). "Moreover, a meta-analysis revealed that chromium reduces the levels of inflammatory biomarkers such as IL-6 and TNF-α, which are major risk factors for hypertension and cardiovascular disease." (PMID 38730326, 2024). "TNF-α has been linked to inflammatory kidney damage caused by hypertension." (PMID 39599656, 2024). "In addition, TNF-α can cause hypertension via stimulating the production of endothelin 1 and angiotensinogen." (PMID 38275420, 2024). "Similarly, the risk of pregnancy-induced hypertension was higher in individuals whose blood serum had elevated levels of oxidative stress factors such as TNF-α, interleukin-6, and interferon-γ." (PMID 37685488, 2023). "Previous research has demonstrated that inhibiting TNF-α could hold significant therapeutic implications for treating hypertension and its associated end-organ damage." (PMID 38005332, 2023). "Moreover, a meta-analysis showed that a −308G/A polymorphism in the tumor necrosis factor- α (TNF-α) increases the risk of essential hypertension in the Asian population." (PMID 37201134, 2023). "TNF-α contributes to an increased risk of hypertension and CHD through various mechanisms." (PMID 36012327, 2022). "Concerning this, different studies have found that practices such as cooking with biomass are associated with increased IL-6, IL-8, and TNF-α, neutrophil infiltration, increased oxidative stress, hypertension, and tachycardia, increasing the risk of cardiovascular diseases." (PMID 35534522, 2022). "Furthermore, increased maternal serum levels of IL-6 and TNF-α have been associated with hypertensive disorders during pregnancy." (PMID 36012236, 2022). "However, in the condition of oxidative imbalance due to NO deficiency, such a protective effect of plasma TNF‐α level is compromised, leading to enhanced sodium retention, and thus, caused salt sensitivity and hypertension in eNOSKO mice." (PMID 33345460, 2021). "Comparing the characteristics of patients on TNFα inhibitors with those on other treatments, the only differences found in terms of cardiovascular risk factors were that the former had lower rates of hypertension and lower levels of homocysteine." (PMID 35054229, 2021). "The inhibition of TNFα may have important therapeutic implications for treatment of hypertension and its associated end organ damage." (PMID 32190663, 2020). "Moreover, IL-6 and TNF-α levels can be used as independent risk factors for hypertension in healthy individuals." (PMID 33265898, 2020).